PRL (prolactin)
Diseases named in the same sentence as PRL in open-access papers (continued):
Sharing a sentence is not in itself a finding about the gene and the disease.
depression (continued). "This hypothesis is confirmed by the observation that in patients with major depression, after electroconvulsive therapy, pharmacotherapy, and psychotherapy, high PRF (prolactin secretion responses to fenfluramine) was positively correlated with responses to treatment." (PMID 36833950, 2023). "Adolescent coeliac disease patients with depression had significantly lower pre-diet tryptophan/ competing amino-acid (CAA) ratios and free tryptophan concentrations, and significantly higher biopsy morning prolactin levels compared to those without depression." (PMID 15774013, 2005). "Further, we observed a substantial increase in serum T and PRL concentrations, as well as the absence of correlation between PRL concentrations and HAM-D scores during the premenstrual stage of the cycle in patients belonging to the depression group." (PMID 37895130, 2023). "The present data showed that although the Cg1 and PrL contributed to the PTSD symptoms, including fear and depression, the Cg1, PrL, and IL were not involved in the PTSD amelioration after chronic fluoxetine treatments." (PMID 33299494, 2020). "In immunohistochemical staining data, the Cg1 and PrL (but not IL) of the mPFC, as well as the BLA, contribute to PTSD symptoms in fear and depression behaviors." (PMID 33299494, 2020). "The data of the immunohistochemical staining with c-Fos showed that the subareas of the mPFC, including the Cg1 and PrL but not the IL, were involved in footshock-induced PTSD symptoms, such as freezing and depression behaviors." (PMID 33299494, 2020). "The observed negative correlation between baseline PRL levels and responses to drug administration in the CMS model suggests that PRL may predict responses to the pharmacotherapy of depression." (PMID 36833950, 2023). "The contribution of increased concentrations of PRL to the depression symptoms is further confirmed by the moderate negative correlation between β-Arrestin protein concentrations and HAM-D scores and by the absence of a correlation between PRL protein levels and HAM-D scores observed in this study." (PMID 37895130, 2023).
hypogonadism (110 papers, 2006 to 2026). A disorder characterized by decreased function of the gonads. "There was an increase in growth hormone deficiency, hypothyroidism, and hypogonadism, while prolactin levels significantly decreased after treatment." (PMID 41145147, 2025). "Elevated prolactin levels reduce lipoprotein lipase activity, which is associated with hypogonadism, weight gain, and dyslipidemia." (PMID 40650124, 2025). "After 12 months under dopamine agonists, prolactin levels normalized in 36 (60%) patients, 25(42%) recovered from hypogonadism, 17 (55%) from ACTH-deficiency, and 14(28%) from TSH-deficiency." (PMID 40035956, 2025). "Large initial tumor size was a significant negative predictor of recovery for all hormone deficiencies (always p < 0.05), while prolactin normalization was a predictor of recovery of hypogonadism (p < 0.001)." (PMID 40035956, 2025). "It is frequently accompanied by androgen deficiency because high prolactin levels suppress LH production and consequently cause hypogonadism." (PMID 38132234, 2023). "Before surgery, 91 patients (67%) had at least one abnormal pituitary axis (hypogonadism: 62.4%; hypothyroidism: 41%, adrenal insufficiency: 30.8%, growth hormone deficiency: 29.9%; increased prolactin: 50.8%)." (PMID 37222882, 2023). "A 55-year-old male presents with visual loss, hypogonadism, and a serum prolactin of 1200 mU/L (~ 60 ng/ml)." (PMID 37166678, 2023). "These manifestations are partially due to the hypogonadism caused by prolactin, which disturbs hypothalamic–pituitary axis function." (PMID 37720899, 2023). "Studies suggest that increased serum PRL levels are associated with infertility, impotence, and hypogonadism." (PMID 36726821, 2022). "Commonly, normalization of PRL and testosterone levels improves anemia as well as other manifestations of hypogonadism and is associated with bone health status improvement." (PMID 35000899, 2022). "It is generally believed that hypogonadism induced by PRL excess is the primary cause of ED in men with prolactinoma." (PMID 34017310, 2021). "High serum prolactin level hurts spermatogenesis and steroidogenesis through its action on prolactin receptors on Sertoli cells and Leydig cells in the testes to cause hypogonadism by altering the pulsatile release of gonadotrophins." (PMID 34104824, 2021). "The goal of treatment for most patients with prolactinomas is restoration of normal prolactin secretion if there are symptoms directly caused by prolactin excess, and prevention of hormonal/metabolic consequences (eg hypogonadism and osteoporosis)." (PMID 20478050, 2010). "It is probably related to the adverse effects of increased PRL levels on the function of the hypothalamic-pituitary-gonadal axis, which in men is associated with testosterone deficiency and metabolic complications of hypogonadism." (PMID 41244055, 2025). "Prolactin and prolactinoma, which produce prolactin, can cause hypogonadism." (PMID 37886642, 2023). "It has been suggested that high PRL levels may potentially cause hypogonadism in patients with HIV through the inhibitory effect of PRL on the release of the gonadotropin-releasing factor from the hypothalamus." (PMID 36833950, 2023). "The sex differences may relate to higher prolactin with associated hypogonadism having a profound effect on male compared to female bone." (PMID 37608079, 2023). "Chronically elevated PRL levels and hypogonadism are associated with reduced BMD and osteoporosis." (PMID 35000899, 2022). "Therefore, prolactin levels are measured as part of the diagnostic evaluation of women experiencing amenorrhea and in those experiencing oligomenorrhea, galactorrhea, or infertility, as well as of men with hypogonadism or erectile dysfunction." (PMID 38338751, 2024). "Furthermore, atypical antipsychotics may impact bone by increasing prolactin secretion and causing hypogonadism." (PMID 27042348, 2016).
hypogonadism (continued). "Patients with hypogonadism were older (62 ± 15 vs. 57 ± 15 years, p < 0.001) and had higher prolactin levels (22 vs. 14 ng/mL, p = 0.002)." (PMID 41685248, 2026). "An additional advantage of our study was a broader assessment of hormone levels, including gonadotropin (LH) and prolactin (PRL), to enable a better understanding of the mechanism of hypogonadism in the studied groups of patients." (PMID 40283649, 2025). "In line of normalization of PRL levels, hypogonadism significantly improved in 23 out 28 patients with microprolactinoma and in 8 out 11 patients with macroprolactinoma." (PMID 39900728, 2025). "Of note, after PRL normalization, persistency of hypogonadism was negatively impacting the QoL of the patients." (PMID 39900728, 2025). "Overt hypogonadism and hypothyroidism (primary or secondary) were observed in 4 (7%) male patients after PRL normalization." (PMID 39900728, 2025). "After a median follow-up of 78 months (IQR 31–147 months), there was a significant decrease in PRL values along with the control of hypogonadism." (PMID 39904877, 2025). "In contrast, a subgroup of men with prolactinomas who completed the questionnaire both at diagnosis and during dopamine agonist therapy showed improved energy scores following PRL normalization and resolution of hypogonadism." (PMID 39900728, 2025). "While changes in Hb and HCT were not significantly impacting the QoL of women and men, persistence of hypogonadism after PRL normalization, negatively impacted all the QoL scores of men." (PMID 39900728, 2025). "In contrast, generalized clonic–tonic seizures are associated with elevations in neuroendocrine hormones such as prolactin and cortisol which can also influence fertility outcomes which contribute to anovulation and hypogonadism." (PMID 41323226, 2025). "The goals of treatment in male microprolactinoma include serum prolactin normalization, and resolution of hypogonadism and sexual dysfunction with improvement in libido, and restoration of fertility." (PMID 40199840, 2025). "In men, hypogonadism was observed in 73% of patients at baseline, and in 11% after PRL normalization." (PMID 39900728, 2025). "High levels of PRL have been proposed as a potential cause of hypogonadism in HIV patients, primarily due to PRL’s inhibitory effect on the release of gonadotropin‐releasing hormone from the hypothalamus." (PMID 41476991, 2025). "These prolactin reductions also likely contributed to improved testosterone levels, which in turn reversed the patient’s hypogonadism." (PMID 39906261, 2025). "Testosterone is essential for spermatogenesis and sperm maturation, while high prolactin levels can lead to hypogonadism and spermatogenic failure." (PMID 39764557, 2025). "Prolactin levels were also found to be elevated in patients with hypogonadism and macroadenoma (304 μIU/mL; p = 0.033)." (PMID 39337013, 2024). "These tumours come to clinical attention due to sellar mass effect, secondary hypogonadism, and the peripheral effects of prolactin." (PMID 38656635, 2024). "Prolactinomas are common tumours that significantly reduce quality-of-life (QOL) due to sellar mass effect, secondary hypogonadism, and the peripheral effects of prolactin." (PMID 38656635, 2024). "Studies by Trinchieri and Kilic suggested that prolactin inhibits GnRH secretion at the hypothalamic level, leading to secondary hypogonadism." (PMID 39797240, 2024). "Elevated PRL levels can induce secondary hypogonadism by suppressing GnRH, LH, and FSH secretion, leading to reduced testosterone and impaired androgenic inhibition of breast growth." (PMID 39797240, 2024). "The other pathway includes the endocrine regulation of prolactin through gonadotrophin-releasing hormone, which induces hypogonadism." (PMID 37875841, 2023). "Two women with hypogonadism (age at diagnosis of 23 and 35 years) received estrogen replacement after diagnosis, and in both patients their serum PRL remained unchanged." (PMID 37403202, 2023).
hypogonadism (continued). "In their study, 18% of KTRs had hypogonadism at 1 year after KT, mostly in older patients; a decrease in the E2/T ratio and normalization of prolactin were evident 4 weeks after KT8." (PMID 35608374, 2023). "The levels of LH, FSH, and prolactin need to be checked to differentiate secondary (pituitary/hypothalamic) hypogonadism from primary hypogonadism." (PMID 36876281, 2023). "The increased risk of NFALD persists after adjusting for age, total cholesterol level, hypogonadism, and the prolactin level (OR=2.39) in female patients." (PMID 36699040, 2022). "An elevation of the serum prolactin level combined with hypogonadism can inhibit the secretion of gonadotropin-releasing hormone (GnRH)." (PMID 35935323, 2022). "It is widely demonstrated, in fact, that acromegaly induces hypogonadism through different mechanisms, both through direct mass effect on gonadotropic cells and through increased plasma levels of prolactin." (PMID 35364803, 2022). "Treatment with DA in hyperprolactinemic patients can lead to weight reduction possibly by increasing dopaminergic tone, beyond normalization of PRL levels and reverting hypogonadism." (PMID 36704037, 2022). "The risk of NAFLD remained higher in the GHd group after adjusting for age, total cholesterol level, hypogonadism, and the prolactin level (OR=1.85)." (PMID 36699040, 2022). "In a recent retrospective study with a follow-up of only 2 years, hypogonadism persisted in 74% of patients after PRL normalization with Cab; the higher PRL levels and tumor size, the lower the chance of normalizing testosterone levels." (PMID 35000899, 2022). "Her baseline prolactin level was 255,894 μIU/mL with secondary hypogonadism, and pituitary magnetic resonance imaging revealed a giant prolactinoma (2.8 × 3.2 × 4.2 cm3) with suprasellar extension and optic chiasmal compression." (PMID 35488355, 2022). "Patients #1 and #2 presented a central hypogonadism (secondary to surgery and elevated PRL levels); their testosterone levels were kept at the lower limit of the normal range with a transdermal dose sufficient to restore sexual function." (PMID 34173929, 2021). "In such cases, the hypercalcemia is attributable to excessive PRL and hypogonadism and reverses with remission of acromegaly." (PMID 33933067, 2021). "As prolactin inhibits GnRH release from the hypothalamus, this is an additional mechanism of the hypogonadism observed in patients on opioids." (PMID 31511863, 2020). "Possible mechanisms include the direct effect of prolactin on adipose tissue, hypogonadism, and the role of dopamine." (PMID 27525431, 2017). "Literature search has shown that as well as higher prolactin levels in most of the patients with sellar and suprasellar aneurysm there was hypogonadism in 67.5%, adrenal insufficiency in 48.6%, and hypothyroidism in 40.5%." (PMID 26246807, 2015). "As contrast, he had low end normal ACTH, FSH, total T3, free T3, and estriol; high end normal prolactin (11.71 ng/mL), distinctly implicating hypopituitarism-induced hypothyroidism and hypogonadism." (PMID 24520983, 2014). "The resulting hypogonadism, with reduced serum testosterone, is reversible with the reduction of prolactin secretion." (PMID 20205855, 2010). "However, our data suggest how the changes in HCT and Hb did not affect the QoL of both women and men, while persistency of hypogonadism significantly impair the QoL of men after PRL normalization." (PMID 39900728, 2025). "It is associated with hypogonadism and usually improves following successful treatment and normalization of prolactin and testosterone." (PMID 40621322, 2025). "Persistency of hypogonadism was significantly impairing all the QoL scores, while difference in PRL from diagnosis (b = 0.508 [0.159; 0.858], p = 0.007) and age (b= -1.166, [-2.238; -0.94], p = 0.035) were impacting respectively physical function and physical health." (PMID 39900728, 2025).
hypogonadism (continued). "Notably, factors influencing hypogonadism recovery were negatively tumor size (OR 0.924, 95% CI 0.883–0.982, p = 0.010) and positively prolactin normalization following treatment (OR 5.722, 95% CI 2.067–17.842, p = 0.001)." (PMID 40035956, 2025). "study, which is a retrospective study of 141 patients with prolactinoma (41 cystic and 79 solid macroprolactinomas) revealed that cystic prolactinomas often present with larger tumor sizes and higher preoperative prolactin levels, which are independent predictors of hypogonadism." (PMID 41199869, 2025). "However, the only variables that were affecting the QoL of men were hypogonadism, change in PRL levels from diagnosis and age." (PMID 39900728, 2025). "However, given that prolactin normalization significantly impacts hypogonadism recovery, tumor size and its mass effect on the pituitary gland also play a critical role in the recovery of all anterior pituitary axes." (PMID 40035956, 2025). "Interestingly, persistence of hypogonadism was negatively affecting all the QoL of men with normalized PRL, confirming the importance of testosterone in the QoL of men." (PMID 39900728, 2025). "This implied that prolactin could also exert direct effects on bone metabolism in addition to hypogonadism." (PMID 38338751, 2024). "However, as symptoms of hypogonadism persisted, testosterone was added, followed by an increase in prolactin levels, which came back down following the discontinuation of testosterone." (PMID 36835974, 2023). "However, as symptoms of hypogonadism persisted, testosterone replacement therapy was initiated, followed by a more than six-fold increase in prolactin levels." (PMID 36835974, 2023). "In males, impaired BMD and anemia are the main consequences of long-term PRL-induced hypogonadism." (PMID 35000899, 2022). "Additionally, gonadal function and the prolactin level were incorporated into multiple logistic regression model to minimize the effect of hypogonadism on NAFLD." (PMID 36699040, 2022). "Five patients were excluded from the study (four as they did not have pituitary function testing performed and one due to a pituitary mass diagnosed after baseline study investigations demonstrated an elevated prolactin and secondary hypogonadism, prompting a pituitary MRI)." (PMID 34697905, 2021). "This could be an issue in women with mild hypogonadism, and measurements of prolactin levels in women treated with antipsychotics is recommended." (PMID 34945077, 2021). "After normalization of prolactin levels, hypogonadism persisted in 18 patients." (PMID 27525431, 2017). "Therefore, the improvement in RBC parameters could be most likely attributed to the normalization of hypogonadism and the concurrent increase in testosterone levels, due to the normalization of PRL." (PMID 39900728, 2025). "However, it remains unclear whether these differences are attributable to prolactin itself or concurrent hypogonadism." (PMID 38645431, 2024). "While the underlying mechanism remains unclear, this association is possibly related to the longer exposure to increased PRL levels and associated hypogonadism in elderly patients and/or men with non-specific symptoms." (PMID 36814862, 2023). "Even though DA very often obtain reversal of hypogonadism, especially in microP and MP with normal TSH-thyroid and ACTH-adrenal function, gonadal replacement therapy may be necessary in patients with persistent hypogonadism despite lowering/normalization of PRL levels or being resistant to DA." (PMID 35000899, 2022). "Therefore, high circulating levels of prolactin may contibute to hindlimb unloading-induced hypogonadism via inhibition of gonadotropins and testosterone synthesis." (PMID 33663539, 2021).